PPARG (peroxisome proliferator activated receptor gamma)
Diseases named in the same sentence as PPARG in open-access papers (continued):
Sharing a sentence is not in itself a finding about the gene and the disease.
endothelial dysfunction (57 papers, 2007 to 2026). In vascular diseases, endothelial dysfunction is a systemic pathological state of the endothelium (the inner lining of blood vessels) and can be broadly defined as an imbalance between vasodilating and vasoconstricting substances produced by (or acting on) the endothelium. "PPARγ is essential in preventing endothelial dysfunction associated with aging, as impaired endothelial PPARγ causes age-related vascular dysfunction." (PMID 39768147, 2024). "Treadmill exercise training suppressed ER stress (PERK, IRElα, and ATF6) and ameliorated endothelial dysfunction through a PPARγ-dependent mechanism with an increase in NO bioavailability in diabetic arteries." (PMID 33329050, 2020). "PPARγ, on the other hand, holds antioxidant and anti-inflammatory effects in endothelium and has been shown to counteract Ang II-induced endothelial dysfunction." (PMID 32560034, 2020). "The observed dysfunctions due to PPARγ loss were restored once transgenic mice received AT1R blockers, providing evidence that AT1R contributes to the endothelial dysfunction induced by PPARγ inhibition." (PMID 32560034, 2020). "Plenty of studies show a protective role against endothelial dysfunction through the activation of PPARγ." (PMID 31354915, 2019). "As endothelial dysfunction occurs followed the vascular endothelial IR, we next examined the effects of PPARγ expression on endothelium‐dependent vasodilation in vivo." (PMID 30398029, 2019). "Many beneficial effects were suggested for PPARγ activity, starting with influencing endothelial dysfunction." (PMID 29670468, 2018). "This study demonstrates that HTL in vitro or in vivo causes accelerated oxidative stress and endothelial dysfunction, all of which are abrogated by RSG, an agonist of PPARγ." (PMID 25656735, 2015). "It has been shown that disruption of endothelial PPARγ resulted in endothelial dysfunction due to impaired production of NO and induction of oxidative stress." (PMID 23888144, 2013). "Ongoing studies in our laboratory will determine if direct TZD-mediated activation of PPARγ coordinately regulates the production of O2− and nitric oxide at the level of the vascular wall to modulate the development of endothelial dysfunction." (PMID 22829806, 2012). "Chronic administration of rosiglitazone ameliorates endothelial dysfunction through PPARγ-mediated metabolic improvements." (PMID 22190906, 2011). "Vpr was shown to suppress the activity of peroxisome proliferator-activated receptor-gamma (PPARγ), which could lead to vascular remodelling and endothelial dysfunction through enhanced vascular oxidative stress and inflammation." (PMID 40759960, 2025). "PM2.5 exposure can induce insulin resistance (IR) via endothelial dysfunction, affecting hepatic insulin signaling pathways and suppressing the expression of peroxisome proliferator-activated receptors gamma (PPARγ) and PPARα, resulting in hepatic lipid accumulation." (PMID 37780625, 2023). "Here, we will focus on the role of PTMs of PPARγ in endothelial dysfunction." (PMID 37833942, 2023). "The present study was designed to determine whether myeloperoxidase (MPO) mediates HC-induced endothelial dysfunction and the role of the PPARγ agonist pioglitazone (PIO) in attenuating endothelial dysfunction." (PMID 32190383, 2020). "Here, we review the available data and summarize on AGE, PPARγ, inflammation, miRNA, and signaling pathways that contribute to endothelial dysfunction in the development of retinal microvasculopathy and analyze the challenges in understanding the pathology of DR." (PMID 33013692, 2020). "Endothelial PPARγ is essential for preventing endothelial dysfunction with aging." (PMID 33013692, 2020). "In this line, PPARγ agonists can ameliorate oxLDL-induced endothelial dysfunction." (PMID 31354915, 2019).
endothelial dysfunction (continued). "Importantly, disruption of endothelial PPARγ contributes to endothelial dysfunction in vivo, as reduced nitric oxide production in PPARγ−/− aortas was associated with increased oxidative stress and enhanced activation of NFκB in aortic homogenates." (PMID 28053991, 2016). "However, the role of PPARγ signaling in HHcy-induced endothelial dysfunction needs further investigations." (PMID 25656735, 2015). "DHSGT treatment restored decreased PPAR-γ expression levels in the aorta of western diet-fed ApoE KO mice and the beneficial effect of DHSGT on endothelial dysfunction in diabetic atherosclerosis was similar to rosiglitazone (a PPARγ agonist) which is ameliorated in insulin sensitivity." (PMID 25280587, 2014). "Inhibition of PPARγ causes inward remodeling, oxidative stress and endothelial dysfunction of arteries independent of changes in blood pressure." (PMID 23888144, 2013). "Therefore, endothelial dysfunction of maternal mesenteric arteries results from rather indirect effect of PPARγ inhibition in this study." (PMID 23888144, 2013). "It is described that endothelial dysfunction and cancer might share common confounders, namely activation of the Wnt signaling pathway and depression of peroxisome proliferator-activated receptor gamma (PPAR gamma) signaling, which might link endothelial microvascular dysfunction and cancer." (PMID 38520533, 2025). "Consistent with its activation by PPARγ, oral administration of the PPARγ agonist troglitazone augmented renal klotho mRNA expression in Otsuka Long–Evans Tokushima Fatty rats and protected against the endothelial dysfunction induced in this model of atherogenesis." (PMID 30012954, 2018). "Smooth muscle cell selective PPARγ (SMPG) knockout mice, which lack PVAT, exhibited impaired thermogenic activity and endothelial dysfunction." (PMID 37006244, 2023). "The peroxisome proliferator activated receptor-gamma agonist pioglitazone (PGZ suppresses vascular damage and immune dysregulation in murine lupus and improves endothelial dysfunction in other inflammatory diseases." (PMID 35914929, 2022). "A substantial body of in vivo evidence demonstrates that activation of all three PPAR subtypes—via agonists like fenofibrate (PPARα), rosiglitazone (PPARγ), and GW501516 (PPARβ/δ) —confers potent protection against endothelial dysfunction and robustly promotes reparative angiogenesis." (PMID 41216186, 2025). "Disruption of PPARγ signaling can lead to altered expression of genes involved in lipid metabolism, such as fatty acid binding protein 4 (FABP4) and CD36, contributing to the development of a pro-inflammatory state and endothelial dysfunction." (PMID 39062815, 2024). "Hu and his colleagues reported that RBP7 might normally mediate protective effects of PPARγ and that deletion of RBP7 might augment Ang II-induced endothelial dysfunction in mice, implying RBP7 was involved in BP regulation." (PMID 26517713, 2015). "Due to its partial PPARγ agonist effect, telmisartan inhibits vascular ACE activity, AT-R1 expression and increases endothelial NO synthesis, preventing oxidative stress and endothelial dysfunction more effectively than non PPARγ-agonist ARBs." (PMID 20613959, 2010). "PPARα and PPARγ mRNA are greater in young and adult SHR mesenteric arteries compared to WKY (but not in other tissues), and thizaolidinedione PPARγ agonists attenuated remodeling and endothelial dysfunction in mesenteric resistance arteries in response to angiotensin II or endothelin-1." (PMID 28264510, 2017).
glioma (57 papers, 2004 to 2025). A benign or malignant brain and spinal cord tumor that arises from glial cells (astrocytes, oligodendrocytes, ependymal cells). "Then, we assessed the association of PPARD (rs2016520, rs67056409, rs1053049 and rs2206030) and PPARG (rs2920503, rs4073770 and rs1151988) polymorphisms with glioma prognosis." (PMID 32198386, 2020). "Our findings suggested that PPARD and PPARG polymorphisms were associated with glioma risk and prognosis in the Chinese Han population, and further studies are need to confirm our results." (PMID 32198386, 2020). "In this case-control study, we examined the association of PPARD and PPARG polymorphisms with glioma risk and prognosis in the Chinese Han population." (PMID 32198386, 2020). "Then, we conducted log-rank test, Kaplan-Meier analysis and Cox regression model to evaluate the relationship of PPARD and PPARG polymorphisms with glioma prognosis." (PMID 32198386, 2020). "The odd ratios (OR) and 95% confidence interval (CI) were calculated to assess the association of PPARD and PPARG polymorphisms with glioma risk." (PMID 32198386, 2020). "We conducted a case-control study to investigate the association of polymorphisms in PPARD and PPARG with glioma risk and prognosis in the Chinese Han population." (PMID 32198386, 2020). "The results showed PPARG rs2920503 was strongly related to higher risk of high-grade glioma (III + IV) in co-dominant (OR = 2.04, 95%CI = 1.13–3.68, P = 0.018) and recessive (OR = 2.03, 95%CI = 1.15–3.57, P = 0.014) models." (PMID 32198386, 2020). "Another PPARγ synthetic ligand, ciglitazone, produces a rapid dose-dependent loss of mitochondrial membrane potential, along with a rapid overproduction of reactive oxygen species (ROS) in rat glioma cells." (PMID 36362294, 2022). "The effect of PPARG rs2920503 on glioma risk was related to glioma grade (P < 0.05)." (PMID 32198386, 2020). "Therefore, we conducted a case-control study to investigate the association of PPARD and PPARG polymorphisms (rs2016520, rs67056409, rs1053049, rs2206030, rs2920503, rs4073770 and rs1151988) with glioma risk and prognosis in the Chinese Han population." (PMID 32198386, 2020). "We further did stratification analysis of PPARD and PPARG polymorphisms with glioma risk." (PMID 32198386, 2020). "In human glioma cells, it has been shown thattroglitazone activates protein-tyrosine phosphatase-1B (PTP-1B), whichsubsequently reduces phosphotyrosine 705 STAT3 (pY705-STAT3) via a PPARγ-independent pathway.Reduction of pY705-STAT3 in glioma cells caused downregulation of c-FLIP andBcl-2." (PMID 18615184, 2008). "Though rosiglitazone, for example, has been shown to decrease edema following a hemorrhagic event, further studies are required to investigate PPARγ specifically in the context of cerebral edema as a result of an adjacent glioma." (PMID 37554158, 2023). "This can be easily overcome by PPARγ agonists, as demonstrated for pioglitazone in human glioma xenograft model." (PMID 37554158, 2023). "The OS analysis revealed that high PPARG expression was associated with poor prognosis in lower-grade glioma and glioblastoma (GBMLGG), lower-grade glioma (LGG), glioblastoma (GBM), LIHC, THCA, PAAD, and ALL-R." (PMID 38044948, 2023). "Further investigations on the role of PPARγ in glioma microenvironment and ferroptosis are required." (PMID 37554158, 2023). "Amongst those altered signaling pathways, glioma cells express lower endogenous levels of peroxisome proliferator-activated receptor gamma (PPARγ) compared to healthy brain tissue." (PMID 37554158, 2023). "Bexarotene treatment in C6 glioma cells impedes NF-κB activation by amplifying PPARγ expression, leading to the regulation of apoptosis, DNA damage, and ROS production, among other processes, consequently exerting anti-proliferative and cytotoxic effects." (PMID 38066643, 2023).
glioma (continued). "In glioma, a nuclear association between PAK4 and the peroxisome proliferator-activated receptor gamma (PPARγ) regulates epithelial-to-mesenchymal transition, while PPARγ itself mediates the expression and function of DNA damage response genes." (PMID 35883575, 2022). "The aim of this study is to investigate the potential therapeutic effect of PPARγ agonists on maligant glioma." (PMID 36362294, 2022). "Recent studies showed that peroxisome proliferator-activated receptors (PPARs) had effects on the progression of multiple tumors, but the role of PPARD and PPARG in glioma remains poorly understand." (PMID 32198386, 2020). "PPARγ has been observed in transformed neural cells of human and PPARγ agonist interferes with glioma growth and malignancy." (PMID 32198386, 2020). "Then, we explored the association of PPARD and PPARG polymorphisms with OS and PFS of glioma patients." (PMID 32198386, 2020). "Seven polymorphisms (PPARD: rs2016520, rs67056409, rs1053049 and rs2206030; PPARG: rs2920503, rs4073770 and rs1151988) were genotyped using the Agena MassARRAY system in 568 glioma patients and 509 healthy controls." (PMID 32198386, 2020). "Further studies in larger samples with more ethnic groups are needed to validate our results and explore the mechanism of PPARD and PPARG in glioma." (PMID 32198386, 2020). "PPARG agonists exhibit anticancer activity in glioma models, and increases in PPAR function have been implicated in persistent inflammation, while agonists of LXR promote glioblastoma cell death." (PMID 25952672, 2015). "As glioma cells express some PPARγ, we were interested in the potential of PPARγ agonists in increasing the expression of the glutamate transporter EAAT2." (PMID 26046374, 2015). "Our study provides evidence that the PPARγ agonist pioglitazone increases the functional expression of the glutamate transporter EAAT2 in glioma cells." (PMID 26046374, 2015). "To study the mechanistic detail of PPARγ mediated transcriptional regulation of CIDEA in glioma cell, we chose a 1120 bp genomic region (−1000 to +120) on the CIDEA promoter." (PMID 27551468, 2015). "In light of the findings by Romera and colleagues that PPARγ agonists increase astrocytic EAAT2 and subsequently reduce extracellular glutamate, which we show that PPARγ-mediated EAAT2 modulation is also applicable to glioma cells." (PMID 26046374, 2015). "We investigated the role of the peroxisome proliferator activated receptor gamma (PPARγ) agonist pioglitazone in modulating EAAT2 expression in glioma cells." (PMID 26046374, 2015). "Ectopic expression of CIDEA triggered apoptosis, activated JNK, decreased HIF-1α activation and increased PPARγ levels in glioma cells." (PMID 27551468, 2015). "As it has previously been established that PPARγ agonists have cytotoxic and cytostatic activity, we sought to determine if pioglitazone can alter glioma cellular morphology." (PMID 26046374, 2015). "As PPARγ inhibition-induced CIDEA was accompanied by decrease in glioma cell viability, we next investigated the consequences of CIDEA overexpression on glioma cell survival." (PMID 27551468, 2015). "Studies have suggested that the cytotoxic effect of PPARγ agonists on glioma cells is partially mediated by enhanced redox reactions." (PMID 24672773, 2014). "This review presents the case for evaluating the potential of PPARγ agonists as novel adjuvants in the treatment of refractory high grade glioma." (PMID 24672773, 2014). "One of the most well understood responses of glioma cells to PPARγ agonists is a reduction of cellular viability which leads to the induction of apoptosis." (PMID 24672773, 2014). "Both MMP-2 and MMP-9 have independently been found to be down-regulated after treatment with pioglitazone, suggesting the role of PPARγ agonists in reducing glioma cell invasiveness." (PMID 24672773, 2014).
glioma (continued). "A phase II study combining the PPARγ agonist pioglitazone and rofecoxib with low-dose chemotherapy in high-grade gliomas pointed out a moderate benefit and encourages the future use of this cocktail in highly selected patients." (PMID 22654896, 2012). "PPARγ targeting in human glioma and glioblastoma has provided encouraging results in in vitro and in vivo studies when thiazolidinedione is combined with either a statin or a coxib." (PMID 22654896, 2012). "Among neuroepithelial tumors, gliomas, especially glioblastoma and neuroblastoma, have been the most extensively studied as to regard PPARs, and in this context, the PPARγ isotype was the most extensively studied." (PMID 20339586, 2010). "These investigators havesubsequently reported that the PPARγ agonist pioglitazone reduced cellularviability of rat and human glioma cell invitro." (PMID 18725982, 2008). "Glioma cells overexpressing PPARγ-cDNA showed reduced cellular viability afterpioglitazone treatment, whereas treatment of glioma cells overexpressing amutant cDNA lacking transcriptional activity, showed no antineoplastic effects." (PMID 18725982, 2008). "Earlier studies have shown that glioma cells express PPARγ and that the levels of expression can be modulated by specific agonists." (PMID 19018263, 2008). "To study the effect of PPARγ agonists on the expansion of BTSCs from glioma, we first established culture conditions to generate gliospheres in vitro." (PMID 19018263, 2008). "This letter gives a short review on the debate and adds to the current knowledge by applying a PPARγ inactive derivative of the TDZ troglitazone (Rezulin) which potently counteracts experimental glioma progression in a PPARγ independent manner." (PMID 18815619, 2008). "The finding that troglitazone and its derivative Δ2-troglitazone effectivelyinhibit TGF-β release suggests readily available PPARγ activators and structurally related PPARγ inactive compounds ascandidate drugs for adjuvant glioma therapy." (PMID 18815619, 2008). "In some cases, PPARγ activation induces tumor celldifferentiation (e.g., liposarcoma, breast and pancreatic cancer,neuroblastoma, glioma, bladder carcinoma, and lung carcinoma)." (PMID 19043603, 2008). "Peroxisome proliferator-activated receptor gamma agonists inhibited the proliferation and expansion of glioma and gliosphere cells in a dose-dependent manner." (PMID 19018263, 2008). "Toxicity, antiproliferative, proapoptotic, and antimigratory activity of COX-2 inhibitor (celecoxib—CXB) and/or PPARγ agonist (Fmoc-L-Leucine—FL) was examined in vitro on temozolomide resistant U-118 MG glioma cell line and comparatively on BJ normal fibroblasts and immortalized HaCaT keratinocytes." (PMID 38542198, 2024). "Hence, glutamate and PPARγ biology in the process of glioma-induced brain swelling is conceptually challenging." (PMID 37554158, 2023). "The top correlating drug, prostaglandin J2, is a PPARg agonist and has shown anti-glioma activity." (PMID 35408449, 2022). "In several diseases, such as gliomas, neurodegenerative diseases, amyotrophic lateral sclerosis, and multiple sclerosis, the Wnt/β-catenin pathway acts in an opposite way of peroxisome proliferator-activated receptor gamma (PPARγ)." (PMID 34685544, 2021). "Recent research reported that PAK4 interacted with PPARγ to regulate Nox1 in glioma." (PMID 34584017, 2021). "Although no upregulation or correlation with vascular density could be detected in skin squamous cell carcinoma, PPARγ was less expressed in high grade and more vascularized gliomas than in low grade gliomas which display less microvascular density." (PMID 32785018, 2020).